MGST1 (microsomal glutathione S-transferase 1)
Diseases named in the same sentence as MGST1 in open-access papers (continued):
Sharing a sentence is not in itself a finding about the gene and the disease.
tumor (continued). "The effect of MGST1 on DDP resistance was evaluated using the tumor xenograft assay in vivo." (PMID 39850123, 2025). "Notably, GATM and MGST1 were found to be highly expressed in various tumours and showed significant prognostic implications." (PMID 39160643, 2024). "Notably, compared to KPC210-MR cells, MGST1 KO cells exhibited slower tumor growth and enhanced response to MRTX1133 treatment." (PMID 39501138, 2024). "However, genes associated with tumor metastasis and tumor cell proliferation (SPP1, GSTA1, MAL2, and MGST1) were found to be highly expressed in LUSC1, LUSC2, LUSC4 samples." (PMID 35899203, 2022). "Crosstalk between various cellular functions mediated by COL6A2 and MGST1 coordinates tumor cell vulnerability and might define the severity of the ES cells’ damage." (PMID 36428591, 2022). "Similarly, MGST1 was found to be overexpressed in several human malignant tissues where it was shown to protect cells from several cytotoxic drugs as well as by direct detoxification and downstream protection of tumor cells from oxidative stress." (PMID 19735553, 2009). "Toward this end, we investigated MGST1 function in LSCC cells and observed that silencing MGST1 significantly inhibited tumor cell proliferation, migration, and invasion, likely through downstream suppression of PIK3CA, NF-KB, β-catenin and GSK3β." (PMID 40778224, 2025). "The protein expression levels of MGST1, MGST3, ABCG2, and FXYD2 differed among the G1-G4 DDP-resistant tumor tissues." (PMID 32158694, 2020). "Western blotting analysis revealed that six proteins (MGST1, MGST3, ABCG2, FXYD2, ALDH3A1, and GST-ω1) were differentially expressed among G1-G4 DDP-resistant tumor tissues." (PMID 32158694, 2020). "Only two genes (MGST1 and TFPI) were differentially expressed between low and high SF2 groups in both tumour types." (PMID 24466029, 2014). "Besides, MGST1 down-regulation further enhanced DDP-induced elevation in MDA and Fe2+ levels and reduction in GSH concentration in tumor tissues." (PMID 39850123, 2025). "Targeting MGST1 expression could improve MRTX1133 treatment response and inhibit tumor progression, which might represent a promising strategy for PDAC patients with KRASG12D mutations." (PMID 39501138, 2024). "Additionally, eight genes (ABCG2, ALDH3A1, FXYD2, GST-π1, GST-ω1, HMGCR, MGST1, and MGST3) were upregulated among the G1-G4 DDP-resistant tumor tissues." (PMID 32158694, 2020). "Therefore, targeting MGST1 expression to modulate ferroptosis might enhance the efficacy of KRASG12D inhibitor MRTX1133 and inhibit tumor progression, which could be a promising strategy for PDAC patients with KRASG12D mutations." (PMID 39501138, 2024). "It is possible that the insensitivity of tumor cells to this drug resulted in the unchanged expression of ferroptosis signature genes in CFPAC-1 cells, with no increase in MGST1 expression." (PMID 40076525, 2025). "In the univariate Cox model, MGST1 expression with high clinical stage (TNM), poor primary therapy outcome, poor histological type, high tumour invasion, poor histologic grade or lack of radiation therapy was a negative predictor for OS in UCEC patients." (PMID 35218676, 2022). "The results showed that tumor cells from nonmetastatic tumors expressed high levels of MMP1, KRT1, and MMP13 and low levels of MGST1, FAM133A, and FMO3." (PMID 36569924, 2022).
brain disease (1 paper, 2020). "Furthermore, five out of the 12 RG‐specific proteins (COL11A1, RRAS, GLUD1, IFITM3, and MGST1) are involved in human epileptic disorders prompting the hypothesis that modification of the extracellular environment is a common feature in this type of brain disease." (PMID 32378798, 2020).
myopathy (1 paper, 2024). A disease of the muscle in which the muscle fibers do not function properly. "We selected four up-regulated genes for general myopathy (MGST1, AOX1, FASN, PRKCD), CD163 for IBM, and CYP4B1 for titinopathy, aiming to validate their actual expression in our local muscles." (PMID 38600180, 2024). "The top five up-regulated genes in general myopathy are MGST1, AOX1, FASN, PRKCD, and CHRNA1, which have been rarely reported in previous myopathy studies." (PMID 38600180, 2024). "The genes featured for general myopathy indeed showed relatively higher expression trend in the myopathy muscles: MGST1 (RQ 10.34/2.09, p = 0.02), AOX1 (RQ 4.53/2.41, p = 0.42), FASN (RQ 3.75/1.75, p = 0.10), PRKCD (RQ 2.10/1.23, p = 0.19)." (PMID 38600180, 2024).
MGST1 also shares sentences with these, for which no sentence is quoted: adenocarcinoma (1 paper); breast tumor (1); cardiac hypertrophy (1); demyelination (1); fluorosis (1); heart disease (1); hepatocellular carcinoma (1); infection (1); laryngeal carcinoma (1); lung diseases (1); multiple myeloma (1); myocardial ischemia (1); Niemann-Pick disease (1); pancreatitis (1); pseudoexfoliation syndrome (1); sarcoma (1); schizophrenia (1); silicosis (1); type 2 diabetic mellitus (1).